HLA-B (major histocompatibility complex, class I, B)
Diseases named in the same sentence as HLA-B in open-access papers (continued):
Sharing a sentence is not in itself a finding about the gene and the disease.
psoriasis (continued). "Similar observations were reported from the Dublin cohort, where it was also reported that the presence of HLA-B*27 was associated with the early development of PsA among patients with psoriasis but the presence of HLA-C*06 was associated with a delayed onset of PsA29." (PMID 27928500, 2016). "Additionally, certain HLA alleles associated with psoriasis such as HLA-B*57 and HLA-B*27, have been associated with robust viral control of HIV-1." (PMID 25224121, 2014). "Association of ERAP1 with AS is restricted to individuals bearing the HLA-B risk factor for this disease, HLA-B27, whereas in psoriasis the relationship between ERAP1 and HLA-C remains unclear." (PMID 25019531, 2014). "Finally, the provisional association of KIR3DS1+HLA-B Bw4-80I with psoriasis cannot be due to linkage disequilibrium, because KIR3DS1 is located on chromosome 19 which segregates independently of chromosome 6." (PMID 22577363, 2012). "We additionally performed stepwise regression to identify amino acid residues that were independently associated with psoriasis and found Trp156 and Ala24 in HLA-C; Val97, Leu145, Cys67, and Tyr99 in HLA-B; and Gly107 in HLA-A to be markers independently associated with psoriasis." (PMID 22577363, 2012). "Psoriasis patients are more likely to harbor alleles such as HLA-B*57, HLA-B*27, HLA-C*06 (in high LD with the HLA-C 3′UTR deletion polymorphism), and KIR3DS1+Bw4-80I, theoretically resulting in vigorous cytotoxic T cell and NK cell responses upon infection with HIV-1 virus." (PMID 22577363, 2012). "We have also found that rs2442719 in HLA-B is associated psoriasis." (PMID 22125590, 2011). "More importantly we find that rs9468925 in HLA-C/HLA-B is associated with both psoriasis and vitiligo, providing first important evidence that two major skin diseases share a common genetic locus in the MHC, and a basis for elucidating the molecular mechanism of skin disorders." (PMID 22125590, 2011). "Association of major HLA-B serotypes with psoriasis in the GAIN dataset." (PMID 19680446, 2009). "A detailed analysis of HLA-B in both populations demonstrated that HLA-B*57 was associated with an increased risk of psoriasis and HLA-B*40 a decreased risk, independently of HLA-Cw*0602 and the C6orf10 locus, suggesting the potential pathogenic involvement of HLA-B." (PMID 19680446, 2009). "Located 85 kb centromeric to HLA-C, HLA-B has also repeatedly exhibited association with psoriasis." (PMID 19680446, 2009). "Others include obesity, the presence of arthralgia, severe psoriasis, a history of uveitis, nail psoriasis, scalp psoriasis, having a first-degree relative with PsA, and any associated gene (such as human leukocyte antigens [HLA]-B*08, HLA-B*27, HLA-B*38, and HLA-B*39)." (PMID 35407659, 2022). "Therefore, XXbac-BPG154L12.4 may be interacting with a proxy gene of a known psoriasis-associated gene HLA-B." (PMID 30315195, 2018). "Finally, we have discussed the potential role of peptide processing on susceptibility to psoriasis, with the presence of tyrosine at HLA-B position 116 associated with protection against psoriasis, where position 116 is located near the C terminus of the bound peptide." (PMID 22577363, 2012). "First, both HLA-B*57:01 and HLA-B*27:05 remain associated with psoriasis after conditioning on C*06:02 (B*57:01 p = 1.43×10−3, OR = 1.45; B*27:05 p = 4.83×10−4, OR = 1.52) and both remain independently associated with psoriasis in our stepwise regression model." (PMID 22577363, 2012). "To assess whether HLA-B is responsible for the association of rs13437088 with psoriasis risk, we imputed all HLA-B serotypes with CEPH population frequencies >5%, as well as those serotypes previously suggested to be associated with psoriasis (B*13, B*57 and B*58)." (PMID 19680446, 2009).
psoriasis (continued). "In Brazil’s admixed population, limited previous studies have linked psoriasis to HLA-B*57, -B*27, and -C*06, with HLA-A*02∼C*06∼B*57∼DRB1*07∼DQB1*03 as a common haplotype in patients and HLA-B*07 appears to be protective against psoriasis." (PMID 41512531, 2026). "Second, vitiligo and psoriasis share some common susceptibility genes (e.g., IFIH1, BTNL2) and genetic loci (e.g., HLA-C/HLA-B rs9468925)." (PMID 40156617, 2025). "The HLA-B/MICA rs13437088 polymorphism, which has been associated with early onset psoriasis, predicted a better response to etanercept in a study involving 81 Spanish patients." (PMID 37372997, 2023). "The epitope is associated with psoriasis, where KIR3DS1/HLA-A-Bw4 genotype was positively associated with disease susceptibility and KIR3DL1/HLA-B-Bw4-80I was negatively associated." (PMID 34943866, 2021). "For GRU group, rs13437088 [P(T) = 8.09E-17)], located 30 kb centromeric of HLA-B and 16 kb telomeric of MICA (MIM: 600169), had been previously reported to be associated with psoriasis." (PMID 31024629, 2019). "And SNP rs2442719 [P(T) = 4.47E-11], located only 1 kb from the telomeric end of HLA-B (MIM: 142830), also exhibited significant association with psoriasis." (PMID 31024629, 2019). "For example, alleles marked by Asn97, Thr97, and Val97 in HLA-B were associated with psoriasis susceptibility and HIV-1 control while those marked by Arg97 and Ser97 in HLA-B were associated with psoriasis protection and HIV-1 progression." (PMID 22577363, 2012). "For example, rs2395029 within the MHC gene HCP5 and a proxy for HLA-B*57, was identified in a psoriasis GWAS as the SNP with the largest odds ratio, OR = 4.1, p = 2.13×10−26." (PMID 22577363, 2012). "Gly62 is also strongly associated with susceptibility to psoriasis (p = 2.03×10−39, OR = 3.20) but is in high LD with HLA-B Val97 and thus drops out of the final psoriasis model." (PMID 22577363, 2012). "With four regression models obtained, two SNPs rs9468925 in HLA-C/HLA-B and rs2858881 in HLA-DQA2 were repeatedly selected in all models, suggesting that multiple loci outside PSOR1 locus were associated with psoriasis." (PMID 22125590, 2011). "Other genes within this region still cannot be excluded by our analyses; more detailed studies of HLA-B serotypes and MHC haplotypes are required to further elucidate the association of this locus with psoriasis." (PMID 19680446, 2009). "The second locus we observed after adjustment for HLA-C and C6orf10 is between HLA-B and MICA, located 117 kb centromeric to HLA-C, suggesting the potential association of HLA-B or MICA with psoriasis risk." (PMID 19680446, 2009). "Interestingly, some of these HLA alleles were also strongly associated with the development of other diseases, such as seronegative arthritis (HLA-B*27) and psoriasis (HLA-C*01)." (PMID 39185409, 2024). "Of individuals with a ‘mixed form’ of eczema and psoriasis, 42.5% (34/80) had an elevated total immunoglobulin E (IgE) of over 120 kU/L and females demonstrated homozygosity of the region between human leucocyte antigen B (HLA‐B) and DRB1: DRB4 (DR53)." (PMID 35664974, 2021). "According to the most recent genome-wide meta-analysis, association of most of the other loci in the MHC region (including the non-HLA genes) with PsA seemed to be attributable to linkage disequilibrium with the HLA-B/‐C region as previously shown to be the case in psoriasis as well." (PMID 33581710, 2021). "Data from the immunochip studies in psoriatic disease confirmed differences between psoriasis and PsA at the HLA region and suggested that HLA-B amino acid position 45 may be driving this heterogeneity." (PMID 27928500, 2016). "The effect estimate and direction at HLA-B and HLA-A are similar to that reported for psoriasis." (PMID 25651891, 2015).
psoriasis (continued). "rs10782001 in FBXL19, rs1975974 in C17orf51, rs12720356 in TYK2, rs3792876 in SLC22A4, rs6908425 in CDKAL1, and rs13437088 in HLA-B/MICA have previously been associated with psoriasis, but not with type I psoriasis." (PMID 26613086, 2015). "We found that the five most significant amino acid positions for psoriasis occurred at 3 positions within HLA-B (residue 97 [p = 1.58×10−53], residue 67 [p = 4.00×10−45], and residue 70 [p = 1.35×10−40]) and 2 positions with HLA-C (residue 156 [p = 3.89×10−51] and residue 97 [p = 4.56×10−45])." (PMID 22577363, 2012). "We therefore hypothesized that psoriasis susceptibility might be mediated through activation of NK cells through KIR3DS1 and its putative partner HLA-B Bw4-80I." (PMID 22577363, 2012). "This explanatory model is consistent with several observational studies that patients with severe psoriasis and HIV-1 infection tend to carry the HLA-C*06 and HLA-B*27 alleles, because such alleles would trigger the vigorous immune response associated with exacerbation of psoriasis." (PMID 22577363, 2012). "The lymphocyte associated regions containing HLA-B and HLA-C, harbors two genes that have been implicated in multiple GWAS as modifiers of immunological responses, associated with IL-18 levels, HIV-1 control, vitiligo, multiple clerosis, and psoriasis." (PMID 21738480, 2011). "These are suggestive of the involvement of HLA-B in psoriasis etiology." (PMID 19680446, 2009). "In conclusion, we provide evidence that two loci within the HLA region in addition to HLA-C, one near C6orf10 and one near HLA-B, are significantly associated with psoriasis, suggesting that within MHC there are at least three genes moderating susceptibility to psoriasis." (PMID 19680446, 2009). "Adjusting for the HLA-C, two additional loci, one near C6orf10 and one near HLA-B/MICA, have significant associations with psoriasis, which were also observed in an independent Han Chinese dataset, suggesting that within the MHC there are at least three genes moderating susceptibility to psoriasis." (PMID 19680446, 2009). "Additionally, the authors identified several other HLA alleles, such as HLA-B*15:01g, B*57:01, B*57:02g, B*13:02g, B*38:01g, B*37:01g, C*01:02g, C*18:01g, C*12:03g, DRB1*01:02g and DRB1*04:08g which were associated with an increased risk of psoriasis." (PMID 41512531, 2026). "HLA-B*13:02g, B*15:01g, B*37:01g, B*38:01g, B*57:01g, B*57:02g, B*13:02g, C*01:02g, C*06:02g, C*12:03g, C*18:01g, DRB1*01:02g, DRB1*04:08g and DPB1*04:01g alleles were associated with an increased risk of psoriasis (after the Bonferroni correction factor, only the HLA-C*06:02 remained significant)." (PMID 41512531, 2026). "However, the HLA-B*27 status was not statistically significantly associated with co-occurrence of psoriasis, arthritis or inflammatory bowel disease." (PMID 37277844, 2023). "Thus, if HLA screening were shown to be useful in prospective studies of patients with psoriasis, HLA typing for HLA-B*27 may remain the preferred option." (PMID 28821532, 2017). "Psoriasis patients also demonstrate a significant paucity of HLA alleles and variants associated with HIV-1 disease progression, including HLA-B*35 (especially B*35-Px), B*07:02, B*40, C*04:01, C*07, and tyrosine 116 in HLA-B associated with sub-optimal peptide loading." (PMID 22577363, 2012). "Except that rs7770216 in LOC729816 has been reported to significantly interact with rs563495 on rheumatoid arthritis, and rs2251396 has been tagged to classical HLA-B*04601 allele in Japanese population, all others non-HLA loci appear to be novel loci for psoriasis." (PMID 22125590, 2011). "In this study, a family-based association analysis of the PSORS1 locus was performed by analyzing 10 polymorphic microsatellite markers from the PSORS1 region as well as HLA-B, HLA-C and CDSN loci in 163 Chinese families of psoriasis." (PMID 18369457, 2008).
psoriasis (continued). "Several SNPs used as IVs in the psoriasis MR analyses are located in or near genes with known immunological and inflammatory functions relevant to both diseases, such as IL23R, IL13, TRIM27, HLA-A, HLA-B, and TNFAIP3." (PMID 41465162, 2025). "The target population is adults (≥18 years of age) with suspected axSpA with symptom onset at age ≤ 45, back pain ≥ 3 months, diagnosed with anterior uveitis (AU) and/or psoriasis and/or inflammatory bowel disease (IBD) and/or HLA-B 27 positive, and/or imaging suspicious for axSpA." (PMID 39597975, 2024). "The importance of this connection lies in the fact that patients with SpA but without HLA-B*27 positivity, recent infections, psoriasis, or IBD often go unrecognized and inadequately treated." (PMID 34199710, 2021). "GWAS indicated that the HCP5 SNV rs2395029 was a potential marker for abacavir-induced hypersensitivity, a marker for HLA-B*57:01 in populations of mainly Caucasian or Hispanic descent, as well as flucloxacillin drug liver injury, HIV control, and psoriasis and psoriatic arthritis." (PMID 31137555, 2019). "Although RNU6-283P and a known psoriasis-associated gene HLA-B are both located at the same LD region, XXbac-BPG154L12.4 is not in any LD region which contains any known psoriasis associated gene." (PMID 30315195, 2018). "The observation that psoriasis patients and HIV-1 controllers display concordant amino acids within the peptide binding groove of HLA-B suggests the possibility that an unknown psoriasis antigen shares homology with HIV-1 epitopes." (PMID 22577363, 2012). "Some psoriasis loci showed a substantial single-tissue eQTL, primarily in the cardiovascular system (artery coronary: rs240993/KIAA1919, rs9808753/TMEM50B, heart left ventricle: rs11053802/KLRC4, heart left ventricle: rs11053802/KLRK1, rs5063/CLCN6, rs1050414/HLA-B, rs2778031/SPIN1)." (PMID 36320003, 2022). "The heterogenicity between PsA and psoriasis without PsA may be driven by HLA-B amino acid position 4527." (PMID 31583079, 2019). "GWAS have identified 40 loci in patients with psoriasis, many of which are related to immune function, including the endoplasmic reticulum aminopeptidase 1 (ERAP1), whose product is relevant to peptides binding to the MHC class I molecules, especially HLA-C*0602 and HLA-B*2746." (PMID 27928500, 2016). "We also confirm association of PsA with a previously reported psoriasis locus, NOS2, bringing the total number of confirmed, genome-wide significant, PsA loci to 10 including 4 that are PsA-specific (HLA-B, chromosome 5q31, PsA-specific variants within IL23R and now PTPN22)." (PMID 25923216, 2015). "In addition to classical HLA genes such as HLA-C, HLA-B and HLA-DQA2, we also find association of non-HLA genes in the MHC region such as POU5F1, NFKBIL1, NOTCH4, MICA, IER3 and OR12D2 with psoriasis." (PMID 22125590, 2011).
toxic epidermal necrolysis (70 papers, 2008 to 2026). Toxic epidermal necrolysis (TEN) is an acute and severe skin disease with clinical and histological features characterized by the destruction and detachment of the skin epithelium and mucous membranes. "Strong association between HLA-B*1,502 and carbamazepine-induced Stevens-Johnson syndrome and toxic epidermal necrolysis in mainland Han Chinese patients." (PMID 40873549, 2025). "Association of HLA-B*1,502 allele with carbamazepine-induced toxic epidermal necrolysis and Stevens-Johnson syndrome in the multi-ethnic Malaysian population." (PMID 40873549, 2025). "Association of HLA-B*1,502 allele with lamotrigine-induced Stevens-Johnson syndrome and toxic epidermal necrolysis in Han Chinese subjects: a meta-analysis." (PMID 40873549, 2025). "Carbamazepine-induced Stevens–Johnson syndrome and toxic epidermal necrolysis are highly correlated with HLA-B*1502, the allele frequency of which varies according to ethnicity, being most common in some Asian populations." (PMID 37361213, 2023). "Previous studies reveal that allopurinol can cause a spectrum of severe skin reactions, including Stevens-Johnson syndrome and toxic epidermal necrolysis, in patients with the HLA-B*5801 allele." (PMID 35566594, 2022). "Carbamazepine, oxcarbazepine, and cotrimoxazole-induced Stevens-Johnson syndrome (SJS)/Toxic epidermal necrolysis (TEN) were found to be associated with HLA-B*15:02." (PMID 35450046, 2022). "Stevens-Johnson syndrome or toxic epidermal necrolysis in patients treated with carbamazepine are associated with HLA-B*1502 and HLA-B*5801; HLA-B*5701 associates with abacavir hypersensitivity in white HIV patients, but not in Hispanics or Africans." (PMID 34948113, 2021). "In other cases, one of the most widely studied HLA allele variant (HLA-B*15:02) predispose patients to a severe skin hypersensitivity (Stevens-Johnson syndrome/ toxic epidermal necrolysis) reaction when treated with carbamazepine." (PMID 33096746, 2020). "In similar, HLA‐B*15:02 and HLA‐A*31:01 increase the risk of Stevens–Johnson syndrome or toxic epidermal necrolysis in patients treated with carbamazepine or oxcarbazepine." (PMID 33031633, 2020). "In particular, treatment with carbamazepine is strongly associated with a high risk of developing Stevens-Johnson syndrome and toxic epidermal necrolysis (SJS/TEN) in carriers of the HLA-B*1502 allele." (PMID 31427963, 2019). "Severe and life-threatening Stevens Johnson Syndrome and Toxic Epidermal Necrolysis following treatment with the antiepileptic and psychotropic drug Carbamazepine are associated with HLA-B*15:02; whereas carriers of HLA-A*31:01 develop milder symptoms." (PMID 31618895, 2019). "Its allele, HLA-B *1502, plays an important role in the development of such carbamazepine-caused diseases as Stevens–Johnson syndrome and Lyell’s syndrome, but its effect is seen only in Chinese and Malaysian populations." (PMID 31514272, 2019). "Variants in the HLA-B gene are exposed to a greater risk of serious phenytoin-induced cutaneous ADRs: toxic epidermal necrolysis (TEN) and Stevens-Johnson syndrome (SJS)." (PMID 30564130, 2018). "The HLA-B*15:02 allele has also been associated with increased risk of Stevens-Johnson syndrome/toxic epidermal necrolysis after treatment with other aromatic AEDs, including phenytoin, oxcarbazepine, and lamotrigine." (PMID 28082152, 2018). "The HLA-B*15:02 allele was strongly related to carbamazepine-induced Steven-Johnson syndrome (SJS)-toxic epidermal necrolysis (TEN) in Taiwanese and Thai populations." (PMID 25657656, 2014). "In some of our previous studies, we reported that HLA-B*15:02 was highly associated with Carbamazepine-induced Stevens-Johnson syndrome and toxic epidermal necrolysis." (PMID 24476119, 2014).